MIR374A (microRNA 374a)
Synonyms: hsa-mir-374; hsa-mir-374a; MIRN374; MIRN374A; mir-374a
Gene: MicroRNA gene on chromosome X (74,287,286 to 74,287,357, reverse strand). Ensembl gene ENSG00000199168.
Gene Ontology:
Biological process: miRNA-mediated post-transcriptional gene silencing
Homologues: Orthologues: chimpanzee ptr-mir-374a (100% identical), macaque mml-mir-374a (99% identical), pig ssc-mir-374a (93% identical), guinea pig MIR374A (90% identical), dog MIR374A (68% identical), mouse Mir374c (56% identical). Paralogues in human: MIR374B (75% identical).